CCZ1B (CCZ1B vacuolar protein trafficking and biogenesis associated)
Synonyms: C7orf28B; DKFZP586I1023; H_NH0577018.2; MGC19819
Tractability: PROTAC: ubiquitination databases record sites on it.
Gene: Protein-coding gene on chromosome 7 (6,794,134 to 6,826,770, reverse strand). Ensembl gene ENSG00000146574.
Subcellular location: Lysosome membrane
Subcellular location (Human Protein Atlas): Vesicles
Pathways (Reactome):
Vesicle-mediated transport: RAB GEFs exchange GTP for GDP on RABs
Gene Ontology:
Molecular function: guanyl-nucleotide exchange factor activity
Biological process: vacuolar transport; vesicle-mediated transport
Cellular component: Mon1-Ccz1 complex; lysosomal membrane
Genetic constraint (gnomAD): Loss-of-function variants: 18 observed, 23.61 expected, observed/expected ratio (o/e) 0.76, 90% interval 0.53 to 1.13. The synonymous counts are far from expectation, so gnomAD's model fits this gene poorly and the ratio says little. Missense variants: 104 observed, 198.17 expected, observed/expected ratio (o/e) 0.52, 90% interval 0.45 to 0.62. Synonymous variants: 40 observed, 66.63 expected, observed/expected ratio (o/e) 0.6, 90% interval 0.47 to 0.78.
Homologues: Orthologues: chimpanzee CCZ1B (99% identical), dog CCZ1 (96% identical), mouse Ccz1 (96% identical), macaque CCZ1 (95% identical), rat Ccz1 (91% identical), tropical clawed frog ccz1b (85% identical), zebrafish ccz1 (83% identical), Drosophila melanogaster Ccz1 (30% identical), Caenorhabditis elegans ccz-1 (28% identical). Paralogues in human: CCZ1 (100% identical).
Diseases named in the same sentence as CCZ1B in open-access papers:
CCZ1B is named in the same sentence as 2 diseases in open-access papers, as found by Europe PMC text mining. Sharing a sentence is not in itself a finding about the gene and the disease. The quoted sentences say what the papers report.
paraplegia (1 paper, 2023). Complete paralysis of the lower half of the body including both legs, often caused by damage to the spinal cord. "FYCO1 also has interaction potential with CCZ1B involved in vacuolar transport, ZFYVE27 (the spastic paraplegia gene), CXCR6, and SASS6 involved in centriole duplication." (PMID 37629644, 2023).
CCZ1B also shares sentences with these, for which no sentence is quoted: viral infection (1 paper).